TPO (thyroid peroxidase)
Diseases named in the same sentence as TPO in open-access papers (continued):
Sharing a sentence is not in itself a finding about the gene and the disease.
Anxiety (12 papers, 2004 to 2026). Intense feelings of nervousness, tension, or panic often arise in response to interpersonal stresses. "Multivariate Logistic Regression: effect of anti-TPO+ on risk of one anxiety diagnosis considering gender (Female vs Male) and age (≤ 44 vs > 44) effects." (PMID 15317653, 2004). "Association between positivity anti-TPO (anti-TPO+), mood and anxiety diagnosis." (PMID 15317653, 2004). "However, no specific anxiety diagnosis was found to be associated with anti-TPO+, although General Anxiety Disorder showed a strong trend toward association (P < 0.058)." (PMID 16285879, 2005). "Frequency of anti-TPO+ in to the sample according sex and age and one mood diagnosis (OMD) and one anxiety diagnosis (OAD) diagnosis for multivariate logistic regression." (PMID 15317653, 2004). "Patients with anxiety had higher HAMD and PANSS scores, higher serum thyroid stimulating hormone (TSH), anti-thyroglobulin antibody (A-TG), and thyroid peroxidase antibody (A-TPO) levels, higher blood glucose and blood pressure levels, and more patients with psychotic symptoms and suicide attempts." (PMID 37706034, 2023).
asthma (12 papers, 2013 to 2025). "Characteristics of CSU patients: the table describes disease severity (mild, moderate and severe), asthma comorbidity, high total levels of IgE, number of patients with high IgG anti-TPO and high levels of IgE and anti-TPO simultaneously." (PMID 41368041, 2025). "We further confirmed that patients with asthma had increased TPO expression in their bronchial epithelial brushings." (PMID 38889046, 2024). "In contrast, we found that the increase in epithelial cell TPO gene expression in asthma was driven by increases in expression in patient subgroups with high mucus plugs scores." (PMID 38889046, 2024). "Prior studies have shown that IL-13 regulates TPO expression in airway epithelial cells and that patients with asthma have high TPO expression in their bronchial epithelial brushings." (PMID 38889046, 2024). "TPO and LPO are expressed by airway epithelial cells, and we found that TPO gene expression is increased in airway epithelial cells from patients with asthma, especially in those with airway mucus plugging." (PMID 38889046, 2024). "Using tissue sections from 3 patients with asthma from this biobank, we applied immunofluorescence to show immunostaining for TPO in the apical region of ciliated cells in regions that were also positive for a cilia marker (acetylated α-tubulin)." (PMID 38889046, 2024). "Airway epithelial cell expression of TPO is increased in patients with asthma who have airway mucus plugging." (PMID 38889046, 2024). "We explored here if TPO also localizes to the apical membrane of airway epithelial cells in endobronchial tissue sections from patients with asthma available from the UCSF Airway Tissue Bank." (PMID 38889046, 2024). "In this way, we uncovered that increased TPO gene expression in the airway epithelium in asthma was driven by high TPO expression in patients with airway mucus plugging." (PMID 38889046, 2024). "When we used the RNA-Seq database to determine the expression of LPO and TPO in asthma, we found that TPO expression was significantly higher in patients with asthma than in healthy individuals, whereas expression of LPO was not." (PMID 38889046, 2024). "This connection was recently strengthened by a study demonstrating that an iNOS-Dual oxidase-2-thyroid peroxidase metabolome is the basis of nitrogen radicals and subsequent protein nitration in human severe asthma." (PMID 27524861, 2016). "Taken together, these data provide support for the hypothesis that IL-13–driven increases in TPO in airway epithelial cells could explain, at least in part, the mechanism of formation of mucus plugs in severe forms of asthma." (PMID 38889046, 2024). "Together, these data show that, among the 2 epithelial cell peroxidases, TPO may be particularly important in peroxidase-mediated pathological mucus formation in asthma." (PMID 38889046, 2024). "Furthermore, our TPO immunostaining data in endobronchial biopsy tissue from patients with asthma show that TPO protein expression localized to the apical cell surface of ciliated epithelial cells." (PMID 38889046, 2024). "Finally, gene expression for TPO in airway epithelial brushings was increased in patients with asthma with high airway mucus plug scores." (PMID 38889046, 2024). "The TPO was a marker that related to the severity of asthma." (PMID 34759961, 2021). "TPO and its metabolome drives nitrative stress in severe asthma." (PMID 32117613, 2020). "Indeed, because the bronchial brushing data we analyzed had been collected from patients with asthma who had lung image–based mucus plug scores previously measured, we could link TPO gene expression to airway mucus plug scores in the same patients." (PMID 38889046, 2024). "Thyroid peroxidase, originally described as thyroid specific enzyme, has also been identified in human airway epithelial cells as the only peroxidase differentially expressed in severe asthmatics, thus distinguishing them from healthy controls and milder asthma cases." (PMID 27448387, 2017).
asthma (continued). "In previous analysis of this asthma dataset (GSE43696), thyroid peroxidase (TPO) plays an important role in asthma." (PMID 32117613, 2020). "To begin to explore the clinical implications of epithelial cell peroxidase activity for airway mucus plug pathology in asthma, we examined gene expression for LPO and TPO in epithelial brushings from patients with asthma in the Severe Asthma Research Program-3 (SARP-3)." (PMID 38889046, 2024). "In these patients, total IgE, sensitization to mites IgE (atopy), and asthma were more frequent than those in patients with negative anti-TPO IgE at any time." (PMID 31886301, 2019). "The link to other immune pathologies is further demonstrated by the fact that anti-TPO antibodies were also detected in patients affected by non-AD such as asthma patients." (PMID 28536577, 2017).
Encephalopathy (12 papers, 2016 to 2024). Encephalopathy is a term that means brain disease, damage, or malfunction. "Of the 204 patients who presented with encephalopathy, 31 (15.2%) were positive for the anti-TPO or anti-Tg antibody." (PMID 37737161, 2023). "However, it is generally accepted that the diagnosis must include encephalopathy, cognitive dysfunction, and psychiatric features, along with high TPO titers, response to treatment with steroids, and exclusion of another neurological disease." (PMID 33324338, 2020).
follicular carcinoma (11 papers, 2008 to 2025). "This case was previously reported by our group and it joins few other reports of follicular carcinoma in patients with TPO mutations." (PMID 34501348, 2021). "Therefore, follicular cancer is associated with abnormal TPO expression in studies, with a decrease in TPO immunostaining in 80–95 % of follicular carcinomas." (PMID 26300979, 2015). "Differences in TPO expression were observed in minimally invasive follicular carcinoma (MIFC) compared to widely invasive follicular carcinoma (WIFC)." (PMID 26300979, 2015). "In differentiating between follicular adenoma, follicular carcinoma, and the follicular variant of PTC, several biomarkers have proved to be applicable, including LGALS, hemoglobin, epsilon 1 (HBE1), cytokeratin-19 (CK-19), and thyroid peroxidase (TPO)." (PMID 27213120, 2016). "As previously noted by us31 and others, the encapsulated lesions, follicular adenomas and, in particular, minimally invasive follicular carcinomas, which in this study were of the oxyphilic type, were unreliable in their TPO staining and their sole responsibility for the value reductions." (PMID 18031322, 2008). "All follicular epithelial cells from benign, nonoxyphilic lesions showed an intense TPO-positive cytoplasmic staining, while more than 80% of tumour cells of papillary, medullary, undifferentiated and widely invasive follicular carcinomas were TPO negative." (PMID 18031322, 2008). "The majority of follicular adenomas were TPO positive (n = 30), as expected for benign lesions, and two out of the five minimally invasive follicular carcinomas were expectedly TPO negative." (PMID 18031322, 2008). "The majority of adenomas were TPO positive (30/31), but for the minimally invasive follicular carcinomas three were TPO positive and two TPO negative." (PMID 18031322, 2008). "However, one adenoma with oxyphilic metaplasia was judged to be TPO negative, and three minimally invasive follicular carcinomas, also showing oxyphilic metaplasia, were judged to be TPO positive." (PMID 18031322, 2008). "Minimally invasive follicular carcinomas and adenomas were not reliably diagnosed from the NCB, neither by morphology nor by TPO immunostaining." (PMID 18031322, 2008).
gestational diabetes (11 papers, 2013 to 2025). Carbohydrate intolerance first diagnosed during pregnancy. "Only pre-gestational diabetes was significantly associated with anti-TPO antibodies in our study." (PMID 33588796, 2021). "However, amongst the comorbid conditions, only pre-gestational diabetes mellitus (pre- GDM) was found to have a strong association with anti-TPO antibodies (p-value 0.018)." (PMID 33588796, 2021). "According to the results of this research, elevated TSH values and anti TPO antibodies in early pregnancy might be used as additional first-trimester markers to improve screening performance for gestational diabetes mellitus." (PMID 35807200, 2022). "In addition, increased levels of anti-TPO antibodies may affect the development of gestational diabetes." (PMID 41573549, 2025). "Through multivariate logistic regression, it was demonstrated that patient age, TSH 4 IU/mL, and anti TPO Ab > 35 IU/mL are significant predictors of gestational diabetes mellitus that may improve first-trimester pregnancy screening performance, AUC: 0.711; 95% CI: 0.629–0.793." (PMID 35807200, 2022). "They found a decrease in free T3 levels, an increase in thyroid peroxidase antibodies, and a major incidence of gestational diabetes mellitus (GDM) in the low serum Se cohort." (PMID 35204276, 2022). "GDM: gestational diabetes; GH: gestational hypertension; IUGR: intra-uterine growth restriction; TPOAB: thyroid peroxidase antibody; and SCH: subclinical hypothyroidism." (PMID 35719785, 2022). "Through multivariate logistic regression, we demonstrated that significant predictors of gestational diabetes mellitus that may improve first-trimester pregnancy screening performances are patient age, TSH ≥ 4 μIU/mL and anti TPO Ab > 35 IU/mL." (PMID 35807200, 2022).
preeclampsia (11 papers, 2012 to 2025). Preeclampsia is a hypertensive disorder of pregnancy that is characterized by new-onset hypertension with proteinuria presenting after 20 weeks of gestation, and depending on mild or severe forms may initially present with severe headache, visual disturbances, and hyperreflexia. "Specifically, anti-thyroid peroxidase (anti-TPO) antibody positivity has been associated with an increased risk of miscarriage, preeclampsia, placental abruption, premature rupture of membranes and preterm birth." (PMID 40128881, 2025). "This led us to evaluate thyroid autoantibodies (TPO-Ab and Tg-Ab) among pregnant women in the regional cohort, and we did not observe that the thyroid autoantibodies associated with an increased risk of preeclampsia." (PMID 39090762, 2024). "However, maternal parity was an independent risk factor for gestational hypertension [adjusted OR 0.20 (p-value 0.05) for anti-TPO and 0.20 (p-value 0.04) for anti-TG]." (PMID 33588796, 2021). "This study aimed to investigate thyroid function (TSH, free T3, and free T4)/antibodies (anti-TPO and anti-TG) in patients with preeclampsia." (PMID 26124747, 2015). "A separate study adds more to the disputes by confirming higher levels of anti-TPO antibodies in HC subjects compared to patients with gestational hypertension, preeclampsia, or eclampsia." (PMID 26124747, 2015). "While anti-TPO antibodies were significantly higher, anti-TG antibodies were significantly lower in women with preeclampsia." (PMID 26124747, 2015). "In the current study, while anti-TPO antibodies were significantly higher, anti-TG antibodies were significantly lower in women with preeclampsia." (PMID 26124747, 2015). "These two studies agree with Federico Mecacci's study result in 2000; that showed a positive relation between Anti-TPO and Anti TG and preeclampsia." (PMID 22848832, 2012). "The Anti-TPO and Anti-TG-level evaluation and their relationship determination with preeclampsia and eclampsia is what make, our study different from other studies that were previously performed in Iran." (PMID 22848832, 2012). "Furthermore, TPO-Ab positivity was not a risk factor for preeclampsia in this large study." (PMID 39090762, 2024). "Compared to mothers with both antibodies negative, there was a 73% less chance of gestational hypertension with an unadjusted odds ratio being 0.26 (p-value 0.005) for anti-TPO and 0.27 (p-value 0.011) for anti-TG." (PMID 33588796, 2021). "In contrast to anti-TG antibodies and TSH, Sudanese patients with preeclampsia had higher levels of T3 and T4 hormones and anti-TPO antibodies irrespective of parity, gestational age, and hemoglobin levels." (PMID 26124747, 2015).
dyslipidemia (10 papers, 2018 to 2025). "Anti-TPO positivity in subclinical hypothyroidism is associated with a higher degree of dyslipidemia." (PMID 38628593, 2024). "In this study, we aimed to analyze the association between dyslipidemia and anti-TPO antibodies in patients with SCH." (PMID 35317033, 2022). "For early screening and diagnosis of patients at risk of cardiovascular events, it is crucial to study the association between TPO antibodies and dyslipidemia in SCH." (PMID 35317033, 2022). "We conducted a prospective study to examine the association between anti-TPO antibody and dyslipidemia in SCH among the rural population of central India." (PMID 35317033, 2022). "Women with TPO/TgAb positivity and US positivity had a greater risk of central obesity, hyperlipidemia, and metabolic syndrome." (PMID 30405316, 2018). "Additionally, we have found a significant association of dyslipidemia with anti-TPO positivity." (PMID 35317033, 2022). "Concurrently, the pro-inflammatory state fostered by dyslipidemia can directly suppress thyroid peroxidase activity and thyrocyte function, impairing hormone synthesis." (PMID 41255537, 2025). "Components of metabolic syndrome, TPO positivity, and/or total IgE above the URL were found in 54% of subfertile couples, both in men and women, vs. 16% of fertile couples." (PMID 37763034, 2023). "In this study, we aimed to determine the association between anti-thyroid peroxidase (anti-TPO) antibody and dyslipidemia in subclinical hypothyroidism (SCH)." (PMID 35317033, 2022). "There is scant regional data on the relationship between anti-TPO antibodies and dyslipidemia in SCH." (PMID 35317033, 2022). "This study showed an increased incidence of dyslipidemia in patients with elevated anti-TPO antibodies." (PMID 35317033, 2022). "Our findings showed an increased incidence of dyslipidemia in SCH patients with positive anti-TPO antibodies." (PMID 35317033, 2022). "The adjusted odds ratio of metabolic syndrome was increased by about 25.6% and 52.0% in the TPO/TgAb (+) group and TPO/TgAb (+) and US (+) group." (PMID 30405316, 2018). "For anti-TPO antibodies, positive correlations were reported with estradiol, a BMI ≥ 25, LH, FSH, presence of PCOM, TSH, metabolic syndrome, age, body weight, waist circumference, diastolic blood pressure, and postprandial glucose." (PMID 40806651, 2025). "Further, we recommend exploring the role of thyroxine as an intervention to target the problem of dyslipidemia in patients with SCH, particularly in anti-TPO antibody-positive patients." (PMID 35317033, 2022). "Hence, early screening and diagnosis of dyslipidemia are crucial to prevent cardiovascular morbidity and mortality in SCH patients with positive anti-TPO antibodies." (PMID 35317033, 2022). "Hence, early screening and timely diagnosis of dyslipidemia are recommended to prevent cardiovascular morbidity and mortality in SCH patients with positive anti-TPO antibodies." (PMID 35317033, 2022).
Hypertension (10 papers, 2018 to 2025). The presence of chronic increased pressure in the systemic arterial system. "Anti-TPO positivity is associated with subclinical hypothyroidism and hypertension." (PMID 37821852, 2023). "TPO-Ab (+) status has been shown to be associated with hypertension-related latent thyroid damage." (PMID 34230513, 2021). "TPO-Ab (+) is significantly positively associated with SCH especially for SCH with hypertension." (PMID 33007021, 2020). "In addition, this study is also the first study that revealed SCH subtyped by status of hypertension that might determine the association between TPO-Ab and SCH." (PMID 33007021, 2020). "TPO-Ab (+) status is associated with subclinical hypothyroidism and hypertension, but not with subclinical hypothyroidism without hypertension." (PMID 34230513, 2021). "TPO-Ab (+) status is positively associated with subclinical hypothyroidism and hypertension, but not with subclinical hypothyroidism without hypertension." (PMID 34230513, 2021). "The major finding of this present study is that TPO-Ab is significantly positively associated with SCH with hypertension but not with SCH without hypertension in the eu-thyroid population." (PMID 33007021, 2020). "Therefore, TPO-Ab (+) could be positively associated with SCH with hypertension but not with SCH without hypertension." (PMID 33007021, 2020).
Miscarriage (10 papers, 2013 to 2025). A pregnancy that ends at a stage in which the fetus is incapable of surviving on its own, defined as the spontaneous loss of a fetus before the 22th week of pregnancy. "Elevated TPO-Ab levels during pregnancy have been linked to an increased risk of miscarriage and preterm delivery." (PMID 40927297, 2025). "Anti-TPO is associated with a higher risk of pregnancy complications such as placental abruption, miscarriage preterm delivery and pregnancy-induced hypertension." (PMID 36996084, 2023). "ROC analysis revealed a predictive ability of TPO-Ab for miscarriage (AUC=0.75) and TgAb for preterm birth (AUC=0.70)." (PMID 41503315, 2025). "A single RCT evaluated the effect of treatment of euthyroid TPO Ab positive pregnant women on miscarriage and showed a significant reduction in miscarriage rates, as well as the rates of preterm births." (PMID 23762776, 2013).
multinodular goiter (9 papers, 2011 to 2025). Nodular goiter characterized by more than one discrete tissue mass. "Of the HT patients with diffuse thyroid enlargement, 77.7% had elevated titres of anti-TPO-Ab, while 36.9% of our patients with multinodular goiters had elevated titres of anti-TPO-Ab and 63% had low titres of anti-TPO-Ab." (PMID 31428301, 2019). "Organic iodo-compounds have been shown to inhibit thyroid epithelial cell proliferation; therefore, TPO mutations might increase the risk for multinodular goiter due to the lack of these compounds." (PMID 26761947, 2016).